ORC5 (origin recognition complex subunit 5)
Description:
Component of the origin recognition complex (ORC) that binds origins of replication. DNA-binding is ATP-dependent. The specific DNA sequences that define origins of replication have not been identified yet. ORC is required to assemble the pre-replication complex necessary to initiate DNA replication.
Synonyms: ORC5L; Orc5p; ORC5T; PPP1R117
Tractability: Small molecule: a structure with a bound ligand is known. PROTAC: UniProt records ubiquitination sites on it; ubiquitination databases record sites on it; its protein half-life has been measured.
Gene: Protein-coding gene on chromosome 7 (104,126,341 to 104,208,047, reverse strand). Ensembl gene ENSG00000164815.
Subcellular location: Nucleus; Chromosome
Subcellular location (Human Protein Atlas): Nucleoplasm; Cytosol
Pathways (Reactome):
DNA Replication: Activation of the pre-replicative complex; Assembly of the ORC complex at the origin of replication; Assembly of the pre-replicative complex; CDC6 association with the ORC:origin complex; Orc1 removal from chromatin
Cell Cycle: Activation of ATR in response to replication stress; E2F-enabled inhibition of pre-replication complex formation
Gene Ontology:
Molecular function: protein binding; DNA replication origin binding; nucleotide binding
Biological process: DNA replication initiation; regulation of DNA replication; DNA replication
Cellular component: chromatin; chromosome; chromosome, telomeric region; nuclear origin of replication recognition complex; nucleoplasm; nucleus; origin recognition complex
Genetic constraint (gnomAD): Loss-of-function variants: 4 observed, 12.25 expected, observed/expected ratio (o/e) 0.33, 90% interval 0.16 to 0.75. The upper end of that interval is the gene's LOEUF score, 0.75, which puts it in group 3 of 6, group 1 being the genes least tolerant of losing a copy. Missense variants: 140 observed, 144.04 expected, observed/expected ratio (o/e) 0.97, 90% interval 0.85 to 1.12. Synonymous variants: 62 observed, 51.82 expected, observed/expected ratio (o/e) 1.2, 90% interval 0.97 to 1.48.
Homologues: Orthologues: chimpanzee ORC5 (100% identical), pig ORC5 (97% identical), rabbit ORC5 (97% identical), macaque ORC5 (96% identical), dog ORC5 (94% identical), mouse Orc5 (94% identical), rat Orc5 (93% identical), guinea pig ORC5 (90% identical), tropical clawed frog orc5 (74% identical), zebrafish orc5 (66% identical), Drosophila melanogaster Orc5 (37% identical), Caenorhabditis elegans orc-5 (19% identical).
Diseases named in the same sentence as ORC5 in open-access papers:
ORC5 is named in the same sentence as 11 diseases in open-access papers, as found by Europe PMC text mining. Sharing a sentence is not in itself a finding about the gene and the disease. The quoted sentences say what the papers report.
colon cancer (4 papers, 2022 to 2026). "Knockouts of ORC1, ORC2, ORC5, or ORC2/ORC5 in human colon cancer cells yielded viable clones that were able to load MCM onto DNA and replicate their genomes." (PMID 41423967, 2026). "It was identified that HCT116 colon cancer cells initiate DNA replication normally in the absence of ORC5 and ORC2 proteins." (PMID 36362041, 2022).
myelodysplastic syndrome (2 papers, 2013 to 2023). A clonal hematopoietic disorder characterized by dysplasia and ineffective hematopoiesis in one or more of the hematopoietic cell lines. "Third, the ORC5 gene has been linked to adult AML (acute myeloid leukaemia) and MDS (myelodysplastic syndrome), since its chromosomal location is within a region that is frequently deleted in myeloid malignancy patients." (PMID 23662735, 2013). "ORC5 is frequently deleted in acute myeloid leukemia (AML) and myelodysplastic syndrome (MDS) and appears to be a candidate tumor suppressor gene for these diseases." (PMID 36205357, 2023).
Chronic colitis (1 paper, 2014). A chronic inflammatory disease of the large intestine (colon, cecum and rectum). "Thus, the potential DEGs (Orc2 and Orc5) can be used as new and meaningful molecular markers in the evolution process of chronic colitis to colitis-associated CRC in this model." (PMID 24743346, 2014).
lung carcinoma (1 paper, 2023). "The lung cancer dataset showed that the DNA alteration percentages of the ORC complex were 1.9% (ORC1), 1.7% (ORC2), 1.5% (ORC3), 1.2% (ORC4), 2.2% (ORC5), and 1.4% (ORC6)." (PMID 36205357, 2023).
parasitemia (1 paper, 2008). "Re-appearance of ORC5 foci in some parasites and the increase in parasitemia in the presence of caffeine following HU treatment may suggest that DNA damage checkpoint pathways are active in the parasites." (PMID 18554328, 2008).
type 2 diabetes (1 paper, 2023). "In this study, we identified a novel low-frequency variant associated with type 2 diabetes, rs2891691, which lies between the ORC5 and LHFPL3 genes and showed increased accuracy of imputation and association power when using the TOPMed panel." (PMID 37148359, 2023).
cancer (5 papers, 2018 to 2025). A tumor composed of atypical neoplastic, often pleomorphic cells that invade other tissues. "On the other hand, we have generated cancer cell lines in which one of the ORC subunits, ORC1, ORC2, or ORC5, is mutationally inactivated by CRISPR–Cas9, and the cells are still viable and proliferate with DNA replication." (PMID 40530691, 2025). "Yet, it has been possible to select cancer cell lines that have mutations in Orc1, Orc2, or Orc5 and do not express detectable levels of the proteins and yet load MCM2-7 to the chromatin and replicate their DNA as they proliferate in culture." (PMID 40304571, 2025). "Also overexpressed are three members of the origin recognition complex (ORC4, ORC5, ORC6) that were also previously linked to cancer development." (PMID 29416781, 2018). "Our results indicated that the expression of ORC1, ORC2, ORC3, ORC4, ORC5, and ORC6 was different in the seven common types of tumor‐infiltrating immune cells, such as B cells, CD4 T cells, CD8 T cells, NK cells, macrophages, endothelial cells, and cancer‐associated fibroblasts." (PMID 36205357, 2023). "It is also worth noting that in cancer cells in culture, we are seeing a near normal level of loading of MCM2-7 on chromatin when Orc1, Orc2, or Orc5 genes are deleted, and that 60% of the origins of replication remain at the same sites as in WT cells." (PMID 40304571, 2025). "Mapping of origins in cancer cell lines engineered to delete three of the subunits, ORC1, ORC2, or ORC5, shows that specific origins are still used and are mostly at the same sites in the genome as in wild-type cells." (PMID 40530691, 2025). "Cancer cell lines in culture can survive and replicate DNA replication after genetic inactivation of individual ORC subunits, ORC1, ORC2, or ORC5." (PMID 40304571, 2025). "A few human cancer cell lines have been created by CRISPR-Cas9 mediated genome engineering where ORC1, ORC2, and ORC5 cannot be detected by regular immunoblots and yet the cell lines survive, proliferate and replicate DNA with the normal complement of origins of replication." (PMID 40304571, 2025). "Even in humans, ORC1, ORC2, and ORC5, the essential components of the eukaryotic replication initiation complex, are not essential in some cancer cell lines, suggesting that mechanisms of replication initiation rescue may also operate beyond the bacterial kingdom." (PMID 40439200, 2025).
ORC5 also shares sentences with these, for which no sentence is quoted: tumor (4 papers); acute myeloid leukemia (1); colitis (1); intrahepatic cholangiocarcinoma (1).